IL1B (interleukin 1 beta)
Diseases named in the same sentence as IL1B in open-access papers (continued):
Sharing a sentence is not in itself a finding about the gene and the disease.
myocardial infarction (continued). "In several acute myocardial infarction models, both IL-1β signaling and pyroptosis induce amplification of the initial ischemic damage, lead to the expansion of the infarct size, and decrease cardiac contractility and cardiac output." (PMID 34973094, 2023). "A biochemical analysis of acute myocardial infarction identified IL1B as a biomarker of acute myocardial infarction that mediates the inflammatory response after acute myocardial infarction." (PMID 37268894, 2023). "Both cytokines, especially IL-1β, are upregulated in myocardial infarction and other cardiac pathologies and have a role in the progression to heart failure." (PMID 38288352, 2023). "The CANTOS study found that in enrolled patients with myocardial infarction with adequate lipid control, the use of a monoclonal antibody that targets IL‐1β and canakinumab further reduced the incidence of major cardiovascular events." (PMID 36932468, 2023). "Subsequently, the major clinical trial of inhibiting IL-1β with an antibody, canakinumab, administered in patients with myocardial infarction was concluded in 2017 showing a major reduction in cardiovascular mortality in sub-sets of patients." (PMID 37539090, 2023). "In both mice and humans, IL-1β and IL-6 are significantly upregulated following myocardial infarction and with advanced heart failure." (PMID 36440002, 2022). "Although not fully understood, macrophage TFEB inhibition of inflammasomes and IL-1β secretion were also observed in previous studies within atherosclerotic and post-myocardial infarction mice models." (PMID 35228523, 2022). "In contrast, in the recent CANTOS trial an anti-IL-1β monoclonal antibody (canakinumab) reduced HF-related hospitalizations and mortality in patients with previous myocardial infarction, but the system-wide effects and mechanisms of action remain undefined." (PMID 35371099, 2022). "It inhibited NLRP3, IL-1β, and caspase-1 expression in myocardial tissue three days after myocardial infarction." (PMID 36320147, 2022). "Recent studies have reported that IL-1β blockade improved systolic function during myocardial infarction, suggesting that anti–IL-1β antibodies can be used to protect cardiomyocytes against myocardial I/R injury." (PMID 35087030, 2022). "Beginning with MCC950, it was able to alleviate myocardial ischemia/reperfusion injury in a porcine model of myocardial infarction by limiting neutrophil influx into the myocardium and IL-1β levels." (PMID 36555579, 2022). "Lastly, in a large clinical study of 10,061 patients with a previous myocardial infarction, treatment with the anti-IL-1β monoclonal antibody, Canakinumab, resulted in reduced myocardial infarctions." (PMID 35821823, 2022). "Intriguingly, canakinumab and anakinra, two IL-1β antagonists, have been established to effectively prevent the recurrence of ischemic events in patients with prior acute myocardial infarction." (PMID 35052846, 2022). "IL-1β is considered important for recruiting leukocytes, especially neutrophils and monocytes, to the infarcted area after myocardial infarction." (PMID 35514973, 2022). "Anakinra, a receptor antagonist for IL-1β, reduced myocardial remodeling after myocardial infarction in mice." (PMID 35548445, 2022). "We next assessed cardiac expression of CX3CL1 and IL-1β at 3, 14 and 28 days post myocardial infarction using immunoblot analysis." (PMID 36496449, 2022). "In contrast, IL-1β inhibition improves adverse cardiac remodeling after acute myocardial infarction, which includes left ventricle end-systolic volume index, change in CRP levels, and proinflammatory response." (PMID 35425785, 2022). "A recent clinical trial (CANTOS) targeted IL-1β and showed reduced HF-related hospitalization in patients with previous myocardial infarction." (PMID 35371099, 2022). "A double-blind trial using canakinumab, a monoclonal antibody against IL-1β, demonstrated a beneficial effect in preventing the recurrence of myocardial infarction." (PMID 36611853, 2022).
myocardial infarction (continued). "A recent study showed that GSK-3β inhibition alleviated NLRP3 inflammasome activation in myocardial infarction, and subsequently affected IL-1β release." (PMID 36164369, 2022). "In experimental mouse models, IL-1β was reported to be highly expressed in cardiac tissues following acute myocardial infarction." (PMID 35514973, 2022). "Emerging studies have identified that immune cells infiltrate myocardial tissue during myocardial infarction and release a large number of pro-inflammatory cells, including IL-1β, IL-6, IL-17A and TNF-α." (PMID 36483733, 2022). "During myocardial infarction, various pro-inflammatory cytokines including TNFα, IL-6, IL-1β, and TGF-β1 are released, promoting cardiac remodeling." (PMID 35883637, 2022). "The cytokine response to infection is similar in the acute phase to myocardial infarction, and is triggered by DAMPS and danger signals following pathogenic invasion (stimulating IL-6, TNFα and IL-1β)." (PMID 33629195, 2021). "Treating mice with the small molecule MCB-613, a steroid receptor coactivator stimulator,was shown to decrease IL-1β mRNA expression in cardiac fibroblasts following myocardial infarction via single cell analysis." (PMID 34909658, 2021). "At 24 hours after myocardial infarction, increased levels of IL-1β are increased further, and are accompanied by excessive activation of the sympathetic nerves." (PMID 34803503, 2021). "IL-1β has also been identified as one of the most significant triggers in fibrosis following myocardial infarction." (PMID 34909658, 2021). "Patients were randomised to the interleukin-1 beta monoclonal antibody, canakinumab, or placebo; canakinumab administered subcutaneously every 3 months over 3.7 years reduced cardiovascular death, myocardial infarction or stroke compared to placebo." (PMID 33919478, 2021). "Activated NLRP3 inflammasome is an important promoter gene of heart failure, and its downstream inflammatory factor IL‐1β has been used as an important target for the treatment of myocardial infarction in clinical trials." (PMID 34402164, 2021). "Treatment with MCB-613 was shown to greatly reduce fibrotic tissue in murine hearts following myocardial infarction, illustrating the overall effect of IL-1β inhibition and the reduction of inflammation in the microenvironment." (PMID 34909658, 2021). "In this trial, canakinumab (a monoclonal antibody against IL-1β) was examined for its potential in reducing the number and frequency of secondary myocardial infarction (MI) events in cardiac patients." (PMID 32378144, 2021). "On the contrary, CANTOS (Canakinumab Anti-inflammatory Thrombosis Outcomes Study) demonstrated that IL-1β inhibitor canakinumab significantly reduced cardiovascular events in post-myocardial infarction patients with hsCRP levels ≥ 2 mg/L." (PMID 34419168, 2021). "The Cantos trial showed clinical effect of blocking IL-1β in patients with previous myocardial infarction at least 30 days prior to inclusion." (PMID 34135690, 2021). "JC124 was shown to block ASC aggregation, caspase-1 activation, and IL-1β secretion and thus exert protective effects in the mouse models of acute myocardial infarction and in transgenic AD models." (PMID 33534121, 2021). "A double-blind trial of canakinumab, designed to assess the therapeutic effect of a monoclonal antibody against IL-1β, showed beneficial effect in preventing the recurrence of myocardial infarction." (PMID 34210954, 2021). "Circ-NNT or USP46 knockdown or miR-33a-5p overexpression inhibited the expression of pro-caspase-1, cleaved caspase-1, pro-caspase-11, cleaved caspase-11, IL-1β, and IL-18 in A/R cardiomyocytes and attenuated myocardial infarction in I/R mice." (PMID 34845193, 2021). "The pro-inflammatory cytokines released in response to myocardial infarction include IL-1α, IL-1β, IL-6, TNFα, IL-8, IL-18 and small chemokine molecules such as monocyte chemoattractant protein 1 (MCP-1)." (PMID 33629195, 2021).
myocardial infarction (continued). "Since IL-1β and IL-33 signaling impacts on wound repair and fibrosis after myocardial infarction, we divided our patient cohort into patients with ICM and DCM." (PMID 34768376, 2021). "Interleukin 1 beta ( IL-1β) is a potent pro-inflammatory mediator that has been correlated to a number of diseases like myocardial infarction, cardiomyopathy and acute myocarditis." (PMID 34768376, 2021). "Platelet membrane microparticles (PMs) conjugated with anti-IL1β antibody Gevokizumab to neutralize IL1β after acute myocardial infarction and further prevent adverse cardiac remodeling." (PMID 34099630, 2021). "Canakinumab, a monoclonal antibody targeting IL-1β, has been shown to reduce the adverse cardiac event (myocardial infarction and/or stroke) by 15% in patients with a prior MI." (PMID 33995071, 2021). "NF-κB is implicated in the expression of many downstream proinflammatory genes, such as Cox-2, TNF-α, IL-1β, and IL-6, which are involved in the inflammation response in myocardial infarction and myocardial ischemia/reperfusion." (PMID 34304702, 2021). "Subjects who had already had a myocardial infarction and had elevated levels of high-sensitivity C-reactive protein were treated with a blocking antibody to IL-1β, and cardiovascular death, myocardial infarction, or stroke were evaluated." (PMID 32118048, 2020). "The down‐regulation of TNF‐α, IL‐1β and IL‐6 has been found to exert an anti‐inflammatory effect on the development of myocardial infarction." (PMID 32783282, 2020). "Myocardial infarction and reperfusion injury have been associated with the activation of pro-inflammatory cytokines such as TNF-α, IL-1β, and IL-6, and this activation promotes leukocyte activation and extravasation into the LV infarcted area." (PMID 33313409, 2020). "The therapeutic value of antagonising IL‐1β was recently explored in the CANTOS trial, a study of patients at high risk of secondary myocardial infarction." (PMID 33204425, 2020). "It has been reported that plasma levels of IL-1β were increased in the early phase of acute myocardial infarction and that the increase was observed prior to the peak plasma levels of brain natriuretic peptide/BNP." (PMID 32393333, 2020). "In the CANTOS trial, Canakinumab, a human monoclonal antibody targeting interleukin 1 beta (IL-1β), was administered to patients who had previously suffered a myocardial infarct and raised circulating CRP levels." (PMID 32062794, 2020). "MiR-375 regulates the expression of pro-inflammatory cytokines such as IL1-β, TNFα, and IL-6: therefore, miR-375 decrease also reduces cytokine expression, as shown in a myocardial infarction model." (PMID 32547539, 2020). "On the other hand, enhanced IL-1β levels are involved in left ventricular remodeling after myocardial infarction." (PMID 32116755, 2020). "A prime example of this is the CANTOS trial targeting IL‐1β as secondary prevention after a myocardial infarction." (PMID 33204425, 2020). "Nevertheless, only patients with stable CHD are candidates for a therapy with canakinumab, since experimental data showed that IL-1β blockage in the acute phase of a myocardial infarction increased the occurrence of ventricular rupture." (PMID 31325043, 2020). "Pro-inflammatory cytokines such as IL-1β contribute to defective excitation-contraction coupling and arrhythmogenesis in the post-myocardial infarction heart." (PMID 32116751, 2020). "Targeting interleukin 1 (IL-1β), the principal cytokine of innate immunity, in patients with previous myocardial infarction (MI) has been shown to reduce subsequent adverse cardiovascular outcomes." (PMID 32965237, 2020). "In acute myocardial infarction rat model, the combination of pFUS + MB results in increased expression of IL‐1β, 4, 6, MCP‐1 and TNF‐α within 15 minutes post‐sonication." (PMID 33067927, 2020).
myocardial infarction (continued). "The reduction of the IL-1β serum level is associated with a smaller area of the affected myocardial tissue, which explains the role of IL-1β in the pathophysiology of acute myocardial infarction." (PMID 31205590, 2019). "In the case of myocardial infarction (MI), IL-1β is markedly upregulated in infarcted myocardium and in blood, paralleling peripheral cell blood counts." (PMID 31032261, 2019). "The landmark Canakinumab Anti-inflammatory Thrombosis Outcome Study (CANTOS) inhibited interleukin 1β (IL-1B) in survivors of myocardial infarction and reduced cardiovascular events." (PMID 31032261, 2019). "For example, BC166504 co-expresses with 4 mRNAs involved in myocardial infarction: B4galt1, Eln, Il1b and Nfkbiz." (PMID 31827539, 2019). "And it’s reported that IL-1β is an important proinflammatory mediator, its antagonist depress cardiomyocyte apoptosis induced by myocardial infarction." (PMID 31681001, 2019). "Canakinumab, a monoclonal antibody (mAb) directed against interleukin-1β (IL-1β), significantly reduced adverse CV outcomes in patients with a history of myocardial infarction (MI) and elevated C-reactive protein (CRP)." (PMID 29755478, 2018). "Canakinumab, a fully human monoclonal antibody that neutralizes interleukin (IL)-1β, significantly reduced the rate of recurrent CV events in patients with prior myocardial infarction in the Canakinumab Anti-inflammatory Thrombosis Outcome Study (CANTOS)." (PMID 29644229, 2018). "Morroniside is a major component of C. officinalis, a component of ALWPs, and reduces proinflammatory cytokine IL-6 and IL-1β levels in a rat model of acute myocardial infarction." (PMID 30319390, 2018). "Myocardial infarction in the I group significantly increased the concentrations of all the inflammatory cytokines analyzed, including IL-1β, IL-6 and TNF-α, as well as anti-inflammatory cytokine IL-10." (PMID 29057895, 2017). "Neutralization of IL-1β is the subject of a current clinical trial (NCT01327846) to prevent recurrent cardiovascular events in patients with a prior myocardial infarction." (PMID 24995121, 2014). "These PICs include tumor necrosis factor-alpha (TNF-α), interleukin-1β (IL-1β) and IL-6, which are released into the circulation early after myocardial infarction (MI)." (PMID 25984330, 2014). "Recent studies show that, following myocardial infarction elicited by coronary artery occlusion, there is an increase in IL-1β levels in the hypothalamus within 24 h after myocardial infarct." (PMID 25202335, 2014). "The present study is established that bone marrow cells were effective for inducing therapeutic angiogenesis in a rat acute myocardial infarction model, the mechanism of which related to an increase in inflammatory cytokines, such as IL-1β, TNF-α and sVCAM." (PMID 18492279, 2008). "IL-1β promotes leukocyte trafficking to the site of myocardial injury by enhancing endothelial adhesion molecule expression and chemokine production, which sustains the inflammatory response after myocardial infarction." (PMID 41511355, 2025). "Moreover, the anti-IL-1β hydrogel safeguards cardiomyocytes from apoptosis by neutralizing IL-1β and inducing M2-type polarization within the myocardial infarction regions, thereby facilitating therapeutic cardiac repair." (PMID 39811465, 2025). "Post hoc analysis of the CANTOS trial suggested that IL-1β inhibition may improve heart failure outcomes after myocardial infarction, although such analyses can only be seen as hypothesis generating, rather than informing clinical practice." (PMID 40796058, 2025). "The downregulation of the biological clock gene BMAL1/CLOCK leads to circadian rhythm disruption and significant elevation of the pro-inflammatory cytokines CCL2, Interleukin-1 Beta( IL-1β), and IL-6 at the site of myocardial infarction in mice fed a high-fat diet, triggering cardiac inflammation." (PMID 40429770, 2025).
myocardial infarction (continued). "Under pathological conditions such as myocardial infarction, the activation of the NLRP3 inflammasome and the formation of NETs can significantly exacerbate myocardial injury, a process closely associated with IL-1β secretion and WPB exocytosis." (PMID 40520933, 2025). "It induces cells to produce and release a multitude of inflammatory factors, such as IL-6, IL-1β, and TNF-α, which mediate the cascade of inflammatory responses, causing the necrosis of cardiomyocytes, an increase in myocardial infarction area, and a decrease in cardiac function." (PMID 40809170, 2025). "For example, selective neutralization of molecules linked to inflammation, including IL-1β, significantly reduces recurrent cardiovascular events in post-myocardial infarction patients without modulating serum LDL cholesterol levels." (PMID 40292571, 2025). "Indeed, the Canakinumab Anti-inflammatory Thrombosis Outcomes Study showed that blocking inflammation with the anti-IL-1β monoclonal antibody canakinumab reduced heart attacks, strokes, and new-onset diabetes among patients with prior myocardial infarction." (PMID 39184952, 2024). "Having demonstrated the role of CoQ10 on the activation of the NLRP3/IL1β pathway and downstream inflammatory response in macrophages, we next explored the impact of CoQ10 on macrophage-mediated inflammation in the context of myocardial infarction." (PMID 38281937, 2024). "The observations suggest that IL-1β, IL-6, and IL-8 play an important role in myocardial infarction pathogenesis and other inflammatory diseases and may contribute to inflammation-resolved damage." (PMID 38543157, 2024). "The data obtained may characterize the contribution of IL-1β to adverse myocardial remodeling after myocardial infarction." (PMID 39590595, 2024). "Furthermore, at 3 days post myocardial infarction in regenerating neonatal mouse hearts, despite being more numerous, macrophages expressed lower levels of Tnfa and Il1b compared to sham-operated animals." (PMID 36271843, 2023). "Furthermore, HU308 (IP 2 mg/kg) has been shown to be successful in the prevention of myocardial infarction damage by reducing inflammatory markers such as IL-1β and TNF-α." (PMID 37631062, 2023). "Similarly, in adult mice after myocardial infarction, there is a significant influx of Ccr2-expressing macrophages at 3 days post injury, which coincides with an increase in Il1b expression." (PMID 36271843, 2023). "In contrast, in the context of myocardial infarction, IL-1β enriched in the ischemic myocardium can activate the NLP3 inflammasome to prime neutrophils, which then reverse migrate into circulation and the bone marrow to release IL-1β and stimulate granulopoiesis." (PMID 38139412, 2023). "The Canakinumab Anti-inflammatory Thrombosis Outcomes Study (CANTOS) trial showed that the pharmacological blockage of IL-1β protected from recurrent atherothrombotic cardiovascular events in patients with a history of myocardial infarction, independently of its lipid lowering-effects." (PMID 36845063, 2023). "Based on the inflammatory and fibrotic markers commonly observed in response to myocardial infarction and development of heart failure, we assessed the expression of mRNA for Tnfa, Il1b,Il6, Il18, Ccl2, Ccl3, Cxcl1, Cxcl2, Col1a1, Col3a1, Postn, and Tlr4 at 1 and 3 months." (PMID 35411847, 2022). "Furthermore, an animal study revealed that the levels of serum IL-1-β and NF-κB were significantly decreased in rats with myocardial infarction after intervention with Ilex Pubescens." (PMID 35734399, 2022). "In addition, the 315C/T nucleotide transition of the IL-1β gene probably modulates IL-1β protein synthesis and is associated with such cardiovascular diseases as CSFP, coronary artery disease, and myocardial infarction." (PMID 35773625, 2022).